IL6 (interleukin 6)
Diseases named in the same sentence as IL6 in open-access papers (continued):
Sharing a sentence is not in itself a finding about the gene and the disease.
cancer (continued). "We also found that blocking IL-6 not only reduced cancer metastasis but also improved the overall effectiveness of ICI therapy." (PMID 40822347, 2025). "1,25-(OH)2D3 downregulates pro-inflammatory cytokines (IL-6, IL-17, TNF-α) and the immunosuppressive cytokine IL-1, thereby mitigating cancer-associated chronic inflammation." (PMID 41246358, 2025). "For the overall group analysis, patients in Groups 1 and 2 displayed similar expression patterns, particularly the downregulation of cancer-associated genes (Fas, NOS2, VEGF-A, NR4A3, MKi67, and EpCAM), as well as the pro-inflammatory cytokine IL-6." (PMID 40359186, 2025). "In the early stage of cancer, proinflammatory cytokines, such as IL-6, IL-8, and TGF-β secreted from cancer cells, immune cells and stromal cells promote the recruitment of macrophages in the inflammatory TME and their polarization to the M2 phenotype." (PMID 40165901, 2025). "Hepcidin, a peptide hormone regulating iron homeostasis, is often elevated in response to inflammation and cancer, driven by cytokines such as interleukin‐6 (IL‐6)." (PMID 40791284, 2025). "LncRNA-NEF, an oncogene involved in cancer biology and postmenopausal OP, was found to be downregulated in the plasma samples of OP patients while IL-6 was upregulated compared to healthy controls." (PMID 40362509, 2025). "High IL6 levels in cancer patients correlate with a transcriptionally quiescent state in CTLs, marked by reduced expression of genes associated with activation and effector function." (PMID 40427188, 2025). "Key molecules for cancer progression were inhibited (IL6, IL4, CXCL8, CXCR4, CXCL12; ICAM1, CD44 and BCL2), and pro-apoptotic BAD was activated." (PMID 41595551, 2025). "The relationship between IL-6 and clinical parameters, as well as oncological outcomes in cancers, has been extensively investigated over the past two decades." (PMID 39858048, 2025). "Further stratified analyses with larger sample size are needed to evaluate the effects of IL-6 on different types of irAEs and the prognostic correlation of different types of irAEs in cancer treatment." (PMID 40519900, 2025). "Several cytokines (e.g., interleukin (IL)-8, IL-6, IL-1β) that are elevated in persons with COPD have been previously associated with LC risk (including LCINS) and are important for LC and/or cancer biology." (PMID 40456733, 2025). "Blocking IL-6 signaling sensitized cancer cells to treatment, further establishing the link between immunosenescence and drug resistance." (PMID 40356750, 2025). "In particular, CAFs, as the most abundant cell-type in TME, secrete substances such as transforming growth factor-β (TGF-β), vascular endothelial growth factor (VEGF), and interleukin-6 (IL-6) which can promote and enhance cancer progression." (PMID 39287890, 2025). "For example, the SASP factor TNFα can induce ROS-dependent apoptosis in human-derived cancer cell lines, while IL-6 initiates apoptosis in cultured neoplastic T lymphocytes." (PMID 40374593, 2025). "In TNBC, targeting DCLK1 eliminates the malignant phenotype of cancer cells, enhances chemotherapy efficacy, and stimulates antitumor immunity by inhibiting the IL-6/STAT3 pathway." (PMID 40890855, 2025). "IL-6 is one of the most pivotal cytokines linking cancer-promoting inflammation and immunosuppression." (PMID 40165901, 2025). "Compared to para-cancerous tissues, ESCC tissues exhibited significantly higher IL-6 expression levels (P < 0.001), consistent with findings in other cancers." (PMID 40433391, 2025). "This abundance strictly correlates with the elevated levels of IL-6 and IL-10, advanced cancer stages and poor survival of patients." (PMID 40136652, 2025). "We reported that serum IL-6 levels were significantly higher in patients with CC compared to cancer-free women, with an optimal serum IL-6 cut-off value of 365.1 ng/mL for distinguishing between CC and cancer-free participants." (PMID 41561529, 2025).
cancer (continued). "One RCT demonstrated that AE combined with RT during cancer treatment led to greater reductions in IL-6 compared to high-intensity interval training (HIIT) alone." (PMID 40895542, 2025). "Previous studies have established the role of IL-6 in promoting cancer growth, progression, and immune responses across various cancers 20-23." (PMID 39781345, 2025). "IL‐6 and IL‐10 are pleiotropic cytokines mediating both pro‐ and anti‐tumorigenic roles during cancer development." (PMID 40356340, 2025). "Endometrial CAFs secrete IL-6, which induces cancer cell proliferation through STAT-3 transcriptional activity dependent on c-Myc expression." (PMID 40136652, 2025). "Essentially, in TME, the signaling pathway of IL-6 is considered a malevolent player, due to its function in cancer development and progression." (PMID 40933989, 2025). "We found that ECGs were significantly enriched in the TNF‐α/NF‐κB, KRAS and IL‐6/JAK/STAT3 pathways across nearly all cancer types." (PMID 40576208, 2025). "High IL-10 alongside high IL-6/TNF is sometimes observed in late-stage cancers, indicating a state of chronic inflammatory activation with concurrent immunosuppression." (PMID 41007766, 2025). "Treatments like surgery, chemotherapy, and radiotherapy associated with cancer, alongside psychological stress, can trigger the production of proinflammatory cytokines such as IL‐1, INF‐α, IL‐6, and TNF‐α." (PMID 40387308, 2025). "Here we show that CD109 plays a pivotal role as an essential regulator of IL6Rα expression and IL-6-driven oncogenic processes, enhancing cancer cell stemness and antioxidant capabilities in SCC cells." (PMID 40317079, 2025). "Cytokines such as IL-6 play a key role in the systemic effects of cancer, including cachexia and neuropsychiatric symptoms." (PMID 41009413, 2025). "Non-TB studies demonstrate that chronic inflammation (elevated IL-6 and CRP) is associated with increased cancer risk." (PMID 40475250, 2025). "Based on single-cell RNA sequencing, circulating CTLs from cancer patients with high plasma levels of IL-6 show suppressed functional characteristics, and IL-6-STAT3 signaling inhibits classical cytotoxic differentiation of CTLs in vitro." (PMID 40040705, 2025). "It was reported that IL-6 promoted distant metastasis of tumors by promoting epithelial mesenchymal transformation of cancer cells." (PMID 40839565, 2025). "In conclusion, we delineate a mechanistic link from chronic inflammation to failure of lipid homeostasis and lysosome-limited autophagy, identifying the IL-6/CERS axis as a key driver and therapeutic entry point of cancer-associated hepatic dysfunction." (PMID 41256541, 2025). "The presnt study investigated how CAFs contribute to L-OHP resistance in CRC, focusing on IL-6 secretion and its impact on cancer cell survival." (PMID 40718440, 2025). "In cancer, especially advanced stages, inflammatory cytokines like interleukin‐6 (IL‐6) are elevated, which in turn stimulates hepcidin production." (PMID 40791284, 2025). "SASP factors like IL-6 and IL-8 are key in mediating the tumor-promoting effects of senescent cells, fostering a chronic inflammatory microenvironment that aids cancer growth." (PMID 40149983, 2025). "Here, we investigated the metabolic activity of PANC-1, SW620, and MCF-7 cancer cells following treatment with TGFβ-1, IL-6, and HGF at predetermined concentrations." (PMID 40227834, 2025). "The interleukin-6 (IL-6) is critical for several physiological processes, such as inflammation and cancer." (PMID 40141175, 2025). "IL6 and TNF are expressed more in the cancer tissue than in the control endometrium which is opposite of what is seen in plasma samples, where both IL6 and TNF are higher in the control subjects." (PMID 40642843, 2025). "We observed that serum IL-6 levels were comparably higher in patients with CC than in cancer-free women, giving an optimal discriminatory cut-off value of 365.1 ng/mL." (PMID 41561529, 2025).
cancer (continued). "Many studies tried to evaluate the correlation between cytokines and the pathogenesis of various cancer types and IL-2, IL-6, IL-10, and TNF-α are often target of these analyses." (PMID 40869161, 2025). "In prostate cancer models, sevoflurane increased cancer cell invasion and lung metastasis by increasing macrophage M2 polarization through the Il-6/HO-1 pathway, again demonstrating its potential to facilitate cancer metastasis and worsen clinical outcomes." (PMID 40765592, 2025). "Consistently, RCTs in cancer populations have shown that 12 weeks of high-intensity AE lead to greater improvements in IL-6 and IL-10 compared to moderate-intensity AE." (PMID 40895542, 2025). "Despite the potential clinical utility of IL-6 levels in cancer patients receiving ICIs, there is a need for new reliable validated biomarkers for irAE prediction." (PMID 41019062, 2025). "IL-6 levels were lowest in controls (mean 4.54 pg/mL) and elevated in benign tumors (mean 42.01 pg/mL) and malignant tumors (mean 28.80 pg/mL)." (PMID 41149076, 2025). "IL-6 and STAT3, in particular, have been experimentally linked to fatigue in cancer patients due to their roles in cytokine signaling and mitochondrial dysfunction." (PMID 40435272, 2025). "Cancer cells can induce a persistent, low-grade systemic inflammatory state by releasing various cytokines and chemokines, such as interleukin-6 (IL-6) and tumor necrosis factor-alpha (TNF-α)." (PMID 41141695, 2025). "We observed that MyD88, p-ERK, p-NF-kB, TNF-α, IL-1β, and IL-6 were significantly suppressed in cancer cells treated with SsnB compared to the control groups." (PMID 40143078, 2025). "For example, cancer cell-derived EVs carrying HSP90-alpha promote the secretion of IL-6 and IL-8 by monocytes and neutrophils, resulting in CD8+ T cell suppression and reduced efficacy of anti-PD-1/PD-L1 treatment." (PMID 40574844, 2025). "For instance, a longitudinal study illustrated that increased sleep duration or decreased SD were associated with the attenuation of pro-inflammatory biomarkers (such as IL-1β and IL-6) and the counter-regulatory cytokine (IL-10) among cancer survivors." (PMID 41470834, 2025). "Cancer cachexia is often accompanied by elevated circulating cytokines like IL-6, IL-1β, and TNF-α as well as acute-phase reactants (CRP, fibrinogen) in patients, resulting in a state of chronic systemic inflammation." (PMID 40572244, 2025). "Another anti-IL-6 antibody, clazakizumab, improved cancer cachexia in NSCLC patients, as shown by biomarker analysis." (PMID 39780187, 2025). "In those studies, no digital technologies were applied, and only isolated cytokines, such as IL-6 or TNF-α were examined in a single type of cancer." (PMID 40498221, 2025). "IL-6 is an inflammatory cytokine involved in various biological processes, including immune dysregulation and cancer." (PMID 40040705, 2025). "Clazakizumab, olokizumab, MEDI5117, and sirukumab are anti‐IL‐6 antibodies currently under evaluation for cancer treatment; however, these agents remain in the early stages of development." (PMID 40166646, 2025). "The relationship between CTCF and IL6 has been evaluated in several biological scenarios distinct from cancer." (PMID 40143084, 2025). "In HCC, CAF-derived IL-6 triggers EMT in cancer cells via activation of the IL-6/JAK/STAT3 axis, which induces transglutaminase 2 (TG2) expression and promotes the mesenchymal phenotype." (PMID 40918452, 2025).
cancer (continued). "Among the biomarkers associated with immune-related adverse events (irAEs) induced by immune checkpoint inhibitors (ICIs) in cancer patients, interleukin-6 (IL-6) has emerged as a key predictive factor." (PMID 41019062, 2025). "Specifically, HERPUD1 silencing reduced the levels of IL-6 and IL-8, known to promote cancer stem cell expansion and chemoresistance, in response to PA." (PMID 41193432, 2025). "Multiple studies have shown higher levels of IL6 in recurrent cancer compared to primary disease, and that inhibition of IL6 – alone or concurrently with another protumorigenic cytokine – resulted in improved disease control." (PMID 40961077, 2025). "IL-6 is also associated with AMPK and NF-κB activation: several mouse cancer models have demonstrated that blocking IL-6 and associated signaling can attenuate cachexia progression." (PMID 41010454, 2025). "MDSC expansion can be promoted by cancer cell-derived EVs carrying PD-L1 via IL-6/STAT3 signaling, enhancing immune suppression and tumor progression in gastric cancer." (PMID 40574844, 2025). "This dysregulation often supports cancer cell survival and proliferation through canonical pathways like NF‐κB, which promotes the autocrine secretion of survival factors such as IL‐6, particularly in multiple myeloma." (PMID 40922674, 2025). "Supernatants from cancer cell lines stimulate macrophages to secrete elevated IL-6, IL-10, MCP-1, IL-8, GM-CSF, PDGF-AA, PDGF-BB, and VEGF." (PMID 40264780, 2025). "Cytokines such as IL-6 and IL-8, which have immunomodulatory effects, are known to promote cancer growth in TME." (PMID 39652104, 2025). "The synergistic effect of IL-6 and IL-17 has been shown to induce the expression of anti-apoptotic proteins in cancer cells, even at molecular concentrations where the individual cytokine effect is negligible." (PMID 41376623, 2025). "Previous studies have demonstrated that IL-6, as a major cancer-related inflammatory cytokine, enhances cell invasion and migration in GBM cells." (PMID 41446725, 2025). "The IL6-JAK-STAT3 signaling has been shown to promote skeletal muscle wasting during cancer cachexia." (PMID 40655023, 2025). "Cytokines, including IL-6, not only promote the regeneration of normal liver parenchyma following injury but also directly support the survival and proliferation of cancer cells." (PMID 41403696, 2025). "Our study found a significant unit increase of 214.9 ng/mL (95%CI: 60.1–369.7, p = 0.007) in serum IL-6 levels among women with CC compared to their cancer-free counterparts." (PMID 41561529, 2025). "Inflammatory cytokines associated with cancer, including interleukin-6 (IL-6), interleukin-1, and tumor necrosis factor-alpha (TNF-α), suppress albumin synthesis and contribute to the development of cancer cachexia." (PMID 40786260, 2025). "The Schwann cells reciprocate with cancer cells and increase adenosine production with enhanced secretion of IL-6, TNFα and NGF, which ultimately have an augmenting effect on cancer proliferation, migration and invasion." (PMID 40002847, 2025). "By analogy with the low immunogenicity of ‘cold’ tumors, this IL-6-mediated immunosuppressive effect decreases the immunogenic potential of cancer cells, thereby reducing both patients’ responsiveness to ICIs and their susceptibility to irAEs." (PMID 41019062, 2025). "Monoclonal antibodies that block IL-6 (e.g., tocilizumab, an IL-6 receptor (IL-6R) antagonist) have shown preliminary promise in attenuating muscle atrophy in cancer patients." (PMID 40572244, 2025). "The cancer surgery only subgroup analysis included seven studies, and the IL-6 level was significantly lower in EA cohort (SMD = −1.75, 95% CI = −2.61 to −0.9, I2 = 93%, Egger’s regression p = 0.01, trim and fill reported no missing studies)." (PMID 40427164, 2025). "Recent study has identified high plasma IL-6 level as a feature of anti-PD-L1 resistance in patients with advanced cancers." (PMID 40255422, 2025).
cancer (continued). "For example, the rate of monocyte-to-macrophage differentiation by IL-6 tended to be increased in severe patients and was highest in the immunosuppressed and cancer virtual patient cohorts and lowest in the COVID-19 reference virtual patient cohort." (PMID 40489562, 2025). "We retrospectively analyzed consecutive patients admitted to a medical intensive care unit in a quaternary academic center with a comprehensive cancer program, extracting clinical and laboratory data, including inflammatory markers and plasma IL-6 levels." (PMID 41155261, 2025). "During malignant states, the constitutive activation of IL-6/17 signaling influences the assembly of the inflammasome complex that triggers inflammatory responses and affects the biology of inflamed cancer cells." (PMID 41376623, 2025). "Crosstalk between fibroblasts and cancer cells via NF-κB activation and IL-6/IL-8 secretion further supports CAF activation." (PMID 40787471, 2025). "This indicates that treatment combining MBIs with gentle physical exercise continuously increases the IL-6 levels in patients with cancer." (PMID 40281902, 2025). "Interleukin-6 (IL-6) and interleukin-8 (IL-8) can activate survival pathways in cancer cells, leading to resistance against apoptosis induced by chemotherapy." (PMID 40356750, 2025). "TAMs play a crucial role in the acquisition of a cancer chemoresistant phenotype, through the secretion of inflammatory cytokines such as IL-6 and TNF-alpha which activate pro-survival programs." (PMID 39981232, 2025). "In summary, we can conclude that MCPIP1 and IL6 are directly linked and that both MCPIP1 and the IL6/JAK2/STAT3 pathway play essential roles in many cancers." (PMID 40874680, 2025). "Further analysis of two ER + human ILC tumors demonstrated stromal expression of IL6, with highest expression seen in CAFs, perivascular-like cells and endothelial cells with relatively low levels in the epithelial cancer cells." (PMID 40597443, 2025). "A large‐scale study on cancer survivors showed that systemic inflammatory markers (e.g., IL‐1α, IL‐1β, IL‐2, IL‐4, IL‐6, IL‐8, IL‐10, TNF‐α, and C‐reactive protein) are closely related to physical, emotional, and cognitive CRF." (PMID 40095296, 2025). "Being pleiotropic, IL-6 displays both pro-inflammatory and anti-inflammatory behavior during cancer development." (PMID 41376623, 2025). "CAFs drive resistance in EGFR-mutant NSCLC by promoting EMT and secreting resistance-inducing factors such as HGF, IL-6, and kynurenine, activating pro-survival pathways in cancer cells." (PMID 40002883, 2025). "In contrast to the protective effects of acute IL-6 production, prolonged IL-6 secretion can contribute to chronic inflammation, thereby positioning IL-6 as a central player in cancer promotion and maintenance." (PMID 39653766, 2025). "Upon exposure to pathogens or damaged tissue, they mature, reduce antigen uptake, upregulate MHC-II and CCR7, and migrate to LN, driving T-cell responses through TNF-α, IL-12, IL-6, and IL-8 secretion, improving cancer treatment outcomes." (PMID 40260236, 2025). "The secretion of anti-inflammatory cytokines, such as IL-6, IL-10, and IL-13, can promote cancer stemness and contribute to the development of therapeutic resistance." (PMID 40800581, 2025). "In the SW1116 cancer cell line, a statistically significant decrease in IL-6 levels was observed in the culture medium following stimulation with ECH147 compared to both untreated cells and EB5-treated cells (p < 0.05)." (PMID 41256010, 2025). "Elevated IL-6 levels in blood serum have been detected across various malignancies, including those affecting the breast, colon, rectum, and lungs, indicating IL-6’s potential involvement in cancer progression." (PMID 39980561, 2025). "Conversely, other research indicates that activation of the JAK2/STAT3 pathway, mediated by IL‐6, can lead to muscle atrophy, with STAT3 inhibition mitigating muscle wasting caused by cancer cachexia." (PMID 39764565, 2025).